CD160 (CD160 molecule)
Diseases named in the same sentence as CD160 in open-access papers (continued):
Sharing a sentence is not in itself a finding about the gene and the disease.
tumor (continued). "Surprisingly, XCL1 and CD160 were predominantly expressed in tumour cells, with a few positive immune cells infiltrated in the stroma." (PMID 39419971, 2024). "We analyzed several types of tumor biopsies by immunohistochemistry using anti-CD160 H3 mAb, previously characterized as able to recognize both CD160-GPI and CD160-TM isoforms." (PMID 38360636, 2024). "The identification of CD160-TM as a potential tumor target on TNBC cells prompted use to investigate the ability of 22B12 to mediate TNBC tumor cell depletion." (PMID 38360636, 2024). "Thanks to the generation of Abs specific for CD160-TM, we identified the TM isoform as a TNBC tumor marker and explore in vivo the potential of CD160-TM targeting for TNBC depletion." (PMID 38360636, 2024). "We here reported the identification of CD160-TM as a tumor marker for TNBC as well as the generation of a specific anti-CD160-TM mAb able to promote TNBC cell depletion." (PMID 38360636, 2024). "Various studies have suggested that the markers of T‐cell exhaustion, such as CTLA‐4, BTLA, LAG‐3, 2B4, TIM‐3, CD160, and PD‐1, induce the functionally impaired state and thereby suppress the proliferation of the exhausted T cells in tumor tissues." (PMID 38204220, 2024). "TIGIT, A2aR, PD-L2 and CD160 signalling dampens Th1 anti-tumour immunity and promotes a Treg phenotype, aiding cancer progression." (PMID 36790524, 2023). "Biopsies from different tumor types were therefore analyzed by immunohistochemistry using the anti-CD160 mAb H3." (PMID 35428910, 2022). "We noted that high BLCA tumor expression of TNFRSF14 or CD160 trended toward improved prognosis compared with either TNFSF14, LTA, or BTLA." (PMID 34858395, 2021). "When the same analyses were done using PEA Oncology II profiling data, 10 proteins correlated to tumor stage (P < 0.05), for example, CD160, TNFRSF4/OX40L, XPNPEP2, SPARC, MAD homolog 5/SMAD5, CPE, hK8/KLK8, WIF‐1, TCL1A, and MIC‐A/B." (PMID 33768639, 2021). "Intratumoral NK cells have reduced CD160 expression and tumor-infiltrating CD160+ NK cells showed signs of exhaustion." (PMID 34445750, 2021). "In contrast, TNFRSF14 binding in cis to BTLA inhibits trans interactions with LIGHT, LTA, or CD160, to maintain NK cells and T lymphocytes in a resting state, thus tuning lymphocyte activation to the surrounding tumor microenvironment." (PMID 34858395, 2021). "We next evaluated the expression of other immune checkpoints associated with T cell exhaustion (e.g. TIM3, CD160, CD244, and CD73), whose ligands are expressed on both myeloid and tumor cells." (PMID 33469002, 2021). "Again, the most frequent immune targets in CD4+ T cells from patients with GBM, in descending order, isolated from the tumor microenvironment were A2aR > PD-1 > CTLA-4 > CD39 > TIGIT > FOXP3 > LAG-3 > CD160 > TIM3 > KIR > CD73." (PMID 32721947, 2020). "They reported that the restriction of CD160 expression to malignant B cells indicates that it is a tumor-specific antigen and an attractive target for the assessment of minimal residual disease in CD160+ B-LPDs." (PMID 32337012, 2020). "In contrast, the frequencies of 2B4+ and CD160+ T cells were similar in peripheral blood and tumor; the frequency of 2B4+ cells was high in both peripheral and tumor-infiltrating CD8 T cells." (PMID 31709176, 2019). "A positive signal was detected with a cytoplasmic and/or plasma membrane location in all TNBC cell lines tested, confirming that CD160 could be constitutively expressed by TNBC tumor cells." (PMID 38360636, 2024). "However, CD27+Ly6C− and CD27+Ly6C+ γδ T cells within the tumor microenvironment expressed the same levels of CD160, NKG2A, NKp46, and CD44, with NKG2A expression in KP tumors being an exception." (PMID 38816652, 2024).
tumor (continued). "Several checkpoint and inhibitory receptors, such as PD-1 (gene name: PDCD1), CTLA4, TIM-3 (HAVCR2), LAG3, CD39 (ENTPD1), CD160, KLRG1, CD96, BTLA, 2B4, and TIGIT, have been implicated in the reduction of immune activity and response in the tumor micro-environment." (PMID 39513882, 2024). "Interestingly, we found that in the C3 immune cluster of ESCC characterised by relatively higher levels of XCL1 and CD160, ~50% of tumours are from the stemness subtype, which presents a significant WNT alteration." (PMID 39419971, 2024). "Our results show that high tumor abundance of the IL2NK phenotype and transcripts for the KLRK1, CD160, and TNFRSF14 receptors are associated with improved survival, whereas high tumor abundance of the SPANK and PDGFD transcripts is associated with poor survival." (PMID 34858395, 2021). "Reduced CD160 expression on NK cells in patients with various hematological malignancies suggests that down-regulation of CD160 may be a novel mechanism of tumor immune escape." (PMID 34659343, 2021). "Finally, high tumor expression of transcripts encoding the activating NK cell receptors, KLRK1 and the CD160–TNFRSF14 receptor–ligand pair, was strongly correlated with the IL-2-expanded NK cell phenotype and improved BLCA prognosis." (PMID 34858395, 2021). "Tim-3, LAG3, BTLA and CD160 were expressed by a mean of <2% of tumor-infiltrating CD8 T cells, and while CD244 (2B4) was present on higher numbers of CD8 T cells in cSCC, the frequencies of CD244+CD8 T cells did not significantly differ between cSCC, NS and blood." (PMID 33479027, 2021). "In contrast, PD-1 and CD160 levels in tumor tissue were downregulated in advanced stages." (PMID 32393998, 2020). "On the other hand, CD160 mRNA level was increased in patients with low grades of tumor budding." (PMID 32393998, 2020). "On the other hand, PD-1 and CD160 mRNA levels were higher in CRC tumor tissues from patients with early stages, indicating that targeting these two ICs in early stages could be more effective than in advanced stages." (PMID 32393998, 2020). "However, level of CD160 mRNA was significantly increased in patients with low grades of tumor budding." (PMID 32393998, 2020). "A variety of inhibitory and stimulatory receptors could co-express on tumor antigen-specific CD8+ T cells (including CD160, KLRG-1, TIM-3, 2B4, BTLA, and LAG3)." (PMID 31708918, 2019). "Within the tumours of treated animals, CTLA-4 blockade gave rise to a significantly altered expression of markers associated with dysfunction (PD-1, Lag-3 and CD160), activation (CD25, GITR and CD38), as well as co-stimulation and development (CD27 and CD127) on mLama4-specific T cells." (PMID 28916749, 2017). "Indeed, it became ineffective for CD160-TM detection in non-native conditions (e.g. after cell fixation, permeabilization or paraffin inclusion; data not shown), preventing the easy and unequivocal demonstration of CD160-TM expression by IHC on TNBC patients' tumor biopsies." (PMID 38360636, 2024). "Furthermore, a previous study using CD160 mice demonstrated that CD160 is important for interferon-γ production mediated by NK cells, and the sufficiency of CD160+ expression may be necessary for controlling tumor development." (PMID 36313261, 2022). "Thus, increased CD160 expression in mbIL21-expanded NK cells may effect proliferation, cytokine profiles, or anti-tumor activity." (PMID 22279576, 2012). "Our data identify CD160-TM as a tumor marker for TNBC and provide a rational for the use of anti-CD160-TM antibodies as therapeutic tools in this tumor context." (PMID 38360636, 2024). "Altogether, these results validate 22B12 mAb as allowing in vitro and in situ specific detection of CD160-TM in TNBC cell lines and tumor biopsies respectively." (PMID 38360636, 2024). "XCL1 or CD160 expression co-localised with LGR6 expression, and co-expression within tumours was seen in 16.3% (16/98) of our cohort for XCL1 and LGR6, and 27.8% (25/90) for CD160 and LGR6." (PMID 39419971, 2024).
tumor (continued). "Among immunoinhibitors, PVRL2, CD160, KDR and VTCN1 were also negatively correlated with LAMP3 expression in many tumours." (PMID 38146591, 2024). "Immunosuppressive molecules, such as PD‐L1, CTLA‐4, TIM‐3, BTLA, CD160, LAG3, and 2B4,73 not only dampen the tumor's immune response but also impact the efficacy of OVs in infecting tumor cells." (PMID 39399642, 2024). "Numerous studies propose its role in tumor progression, immune evasion, and potential implications for cancer therapy, highlighting the significance of the HVEM and CD160 in cancer biology." (PMID 38999968, 2024). "According to this study, PTK6 expression was positively correlated with CD160, IL10RB, and PVRL2 while being negatively correlated with ADORA2A, BTLA, CSF1R, and KDR in the other tumor types." (PMID 38573548, 2024). "We also observed that S1P treatment in tumor cells inhibited the expression of TAP2, CD27, CD160, and ICOSLG genes, which are important for the immune cell activation needed for antitumor responses." (PMID 35289120, 2022). "A protein array on a lysate of tumors treated with MTX alone displayed a more than 1.5 fold increase of CCL17, CXCL11, CD160 and CXCL10, as compared to control tumor lysate." (PMID 36397148, 2022). "In this review, we discuss the characteristics of CD160, its expression in the CLL tumor microenvironment, and its roles in the pathophysiological processes of CLL." (PMID 36420268, 2022). "On this basis, CD160, MMP-9, PTGDS, SLC26A8, and TLR5 were selected as indicators of tumor detection." (PMID 36733384, 2022). "Emerging evidence has demonstrated that CD160 participates in CLL pathogenesis by activating PI3K/Akt-independent pathways and inhibiting apoptosis, consequently activating tumor proliferation and inducing resistance to apoptosis." (PMID 36420268, 2022). "With increased tumor PD-L1, the expression of inhibitory checkpoint molecules (ICMs), including ADORA2A, BTLA, CD160, and PDCD1, was downregulated while the expression of IDO1 was upregulated." (PMID 33754038, 2021). "CD160 was identified on 0.86 ± 0.2%, 0.59 ± 0.2% and 0.82 ± 0.5% of OAC cells in treatment-naïve, post-FLOT and post-CROSS OAC tumour biopsy tissue, respectively." (PMID 33765543, 2021). "Tumor cells use inhibitory signaling pathways in the immune system, such as the PD-1/PD-L1, CTLA-4, LAG-3, Tim-3, and CD160 signaling pathways, to inhibit the function of TILs in the TME, resulting in tumor immunosuppression." (PMID 34513820, 2021). "High tumor expression of TNFRSF14 and CD160, but not TNFSF14, LTA, or BTLA, was associated with improved BLCA patient prognosis, suggesting that the TNFRSF14–CD160 interaction, like KLRK1, is a prominent pathway of NK cell tumor surveillance in BLCA." (PMID 34858395, 2021). "The most frequent immune targets in the CD8+ T cells from the tumor microenvironment, in descending order, of newly diagnosed patients with GBM were A2aR > PD-1 > CD39 > TIGIT > LAG-3 > CTLA- 4 > BTLA > CD160 > CD73 > KIR > TIM3." (PMID 32721947, 2020). "We found that mRNA levels of PD-1, TIM-3, CTLA-4, TIGIT, CD160, CD244, and KLRG1 were elevated in CRC tumor tissue, implicating their potential contribution to CRC development and/or progression." (PMID 32393998, 2020). "Third, we explicitly couple immune phenotypes with tumour evolutionary trajectories, revealing that C4 tumours represent immune‐inflamed “hot” states (PD‐L1/IFNγ upregulated, MES‐like), whereas C2 tumours represent immune‐desert “cold” states (low MHC, CD160 upregulated, PN‐like proliferative)." (PMID 41292185, 2025). "Upon exploration of CD318 interactions with immune proteins, we found that CD96 and CD160 might be interacting with CD318 in COAD cancer, leading to the accumulation of CD8+ T Cells and CD56dim highly cytotoxic NK cells in the tumor microenvironment." (PMID 40725832, 2025).
tumor (continued). "CD160, a glycosylphosphatidylinositol-anchored Ig domain protein that is expressed on NK cells, γδ T cells and a minor subset of CD4+ and CD8+ T cells, is also overexpressed in some ESCC tumours in our study." (PMID 39419971, 2024). "When examining the phenotype of CD27+Ly6C− and CD27+Ly6C+ γδ T cells in KP and KB1P tumor-bearing mice, we found that CD27+Ly6C+ γδ T cells expressed higher levels of CD160, NKG2A, IFNγ, and CD44 in spleen, LN, and lung, analogous to observations made in tumor-naive mice." (PMID 38816652, 2024). "Analysis of CD8+ T cell clusters from spleen and tumour demonstrated that CD137 expressing clusters 2, 7 and 10 co-expressed a large number of markers related to activation/exhaustion (TIGIT, TIM3, PD-1, CD39, CD160)." (PMID 38986249, 2024). "Nevertheless, it is anticipated that the intricate signaling network constituted by BTLA/HVEM/CD160/LIGHT involved in immune response regulation, tumor development and tumor microenvironment could limit therapeutic success." (PMID 37649037, 2023). "Farren and colleagues have shown that the CD160 is overexpressed in malignant B cells, but not in healthy B cells, indicating CD160 as a tumor-specific marker of malignant B lymphocytes." (PMID 35812748, 2022). "In conclusion, we found that analyzing tumor expression of LTA, CD160, and CD40LG represents a novel immune signature that may be useful for predicting prognosis and response to immunotherapy in patients with LUAD." (PMID 35879761, 2022). "The novel combination of LTA, CD160, and CD40LG, may help us understand the immune status of patients with LUAD, but also optimize available tumor immunotherapies." (PMID 35879761, 2022). "Taking into account the upregulation of several ICI parameters on T cells in tumor-bearing animals, we do not exclude that a combination comprising Listeria vaccine and a blockade of CD160, 4-1BBL and/or a combination thereof will be also efficient." (PMID 35173308, 2022). "Finally, we observed graded functions in ILC1 identified by GzmA and CD160, being CD160+ ILC1 better IFN‐γ‐producers, while less cytotoxic than CD160– cells against tumor cells." (PMID 34347289, 2021). "In addition, the importance of PD-1 and CTLA-4, TIM-3, CD160, and CD244 in promoting tumor growth and progression has been reported in preclinical models." (PMID 32393998, 2020). "In addition, KCNN4 demonstrates a negative correlation with CD160, KDR, and KIR2DL1, which are associated with NK and T‐cell activation, as well as tumour angiogenesis." (PMID 40952239, 2025). "The development of biologics targeting HVEM/BTLA/CD160/LIGHT is still in its infancy and will require a deeper understanding on how this pathway works during the process of T cell activation and differentiation and in the interplay tumor, tumor microenvironment, and the anti-tumor immune response." (PMID 37033927, 2023). "Therefore, the ACM secretome may be creating a therapeutic niche for the use of ICBs to harness anti-tumour immunity through blocking inhibitory signalling of TIGIT A2aR, PD-L2 and CD160 on the surface of T cells." (PMID 36790524, 2023). "Moreover, the FcγRs present on phagocytic cells may also recognize anti-CD160 mAbs and activate ADCP against tumor cells." (PMID 36420268, 2022). "Consequently, CD160-GPI was characterized as an activating receptor as its engagement induces early NK cell cytotoxicity through a PI3-kinase-dependent pathway, potentiates IFN-γ, TNF-α, IL-6 and IL-8 cytokine production and plays a role in the early control of tumor growth." (PMID 35428910, 2022). "By using a specific but conformation-dependent anti-CD160-TM Ab, we established that CD160-TM, but not CD160-GPI, was expressed by TNBC tumor cells." (PMID 38360636, 2024). "Nevertheless, this set of data ruled out an expression of CD160-GPI isoform and favored an exclusive expression of CD160-TM isoform by TNBC tumor cells." (PMID 38360636, 2024).
tumor (continued). "As expected, 22B12 mAb allowed CD160-TM detection on paraffin-embedded or fixed cells, and more importantly on TNBC patients' tumor biopsies but not on healthy breast tissues, suggesting that it might represent a valuable tool for TNBC pre-therapeutic phenotyping." (PMID 38360636, 2024).
cancer (50 papers, 2013 to 2025). A tumor composed of atypical neoplastic, often pleomorphic cells that invade other tissues. "Our results suggested that age might be a confounder for the cancer associated aberrant methylation of CD160, ISYNA1 and RAD51B in the blood." (PMID 35812748, 2022). "Broadly speaking, in canine versus human cancers, the abundances of CD160 and A2AR were greater, while those of NKG2A and OX40 were lower." (PMID 40788962, 2025). "Simultaneously, genes promoting anti-cancer efficacy such as Cd160, Cd244a, and Ccr2 were highly expressed while a relay gene of the NF-κB pathway, Card11, was suppressed in NK cells after CBL0137 treatment." (PMID 39518148, 2024). "Studies have shown that CD160 factors regulate functions of natural killer cells and control potential early cancer therapy." (PMID 38807380, 2024). "These interesting preliminary data warrant further investigation into the detailed pathways of how CD160 expression in cancer cells modulates host immunity." (PMID 39419971, 2024). "Molecular correlation analysis showed that USP20 significantly and positively correlated with the expression of multiple immune checkpoints such as ADORA2A and CD160 in a variety of cancers." (PMID 36874086, 2023). "Bone marrow from AML cancer patients also exhibited downregulation of mRNA expression of CD160, whose protein expression was also found to be downregulated." (PMID 33239726, 2021). "The survival rates of patients with CD160high AML were much higher than those of patients with CD160low cancer, suggesting that CD160 is an antitumor biomarker in AML." (PMID 33239726, 2021). "A close positive correlation between ESRRG and CD160 was also found in predominant cancer types." (PMID 40356747, 2025). "Strikingly, ACACA expression exhibited significant negative correlations with the immune checkpoint-related genes (PDCD1, LAG3, LAGLS9, IDO1, CD244, CTLA4 and TIGIT), while showing positive associations with other genes (TGFBR1, KDR, IL10RB, CD160 and CD274) across most cancer types." (PMID 41169354, 2025). "Similarly, CD160 expression has been identified in specific cancer types, including hematological malignancies and solid tumors." (PMID 38999968, 2024). "Hence, anti-CD160 mAbs can be used as a potential antiangiogenic treatment in ocular diseases and cancer." (PMID 36420268, 2022). "Furthermore, it has also been considered for therapeutic intervention in cancer patients, according to the anti-angiogenic effect of CD160 antibodies on growing endothelial cells." (PMID 30483269, 2018). "After exclusion criteria were applied, six genes (GBA, ATG10, TRIM27, CD160, ISYNA1, RAD51B) were selected for validating the associations between DNA methylation and BC with MassARRAY EpiTyper assays in validation I (48 sporadic BC cases and 48 matched cancer-free female controls)." (PMID 35812748, 2022). "Interestingly, disease-associated TEX in chronic infection were further characterized by co-expression of inhibitory receptors TIGIT and 2B4 (as well as some KLRG1 and CD160) while in cancer, TEX more frequently exhibited higher expression of CTLA-4, Lag-3, and CD39." (PMID 32038613, 2019). "Specifically, in most cancer types, ESRRA positively correlates with TNFRSF14, and ESRRG with CD160." (PMID 40356747, 2025). "Understanding the complexation between CD160 and HVEM can furnish relevant information on certain interactions between cancer and the immune system." (PMID 39273224, 2024). "The present analysis found elevated expression of CD47 not only positively correlated with PD1, PD-L1, CTLA4, but also with multiple other immune checkpoints such as IDO1, CD40, CD160, CD86, CD44 across various cancer types." (PMID 35697717, 2022). "In our study, we observed significantly lower methylation of CD160, ISYNA1 and RAD51B in blood DNA of BC patients than that of cancer-free controls in the Chinese population." (PMID 35812748, 2022).